WDR5 (WD repeat domain 5)
Diseases named in the same sentence as WDR5 in open-access papers (continued):
Sharing a sentence is not in itself a finding about the gene and the disease.
pancreatic cancer (continued). "Furthermore, WDR5 deficiency or inhibition causes the significant repression of MHC I expression in vitro and in vivo in pancreatic tumor cells." (PMID 39201460, 2024). "Previous study revealed that WDR5-H3K4me3 epigenetic axis could modulate the expression of OPN to enhance the immune escape of pancreatic cancer." (PMID 37741985, 2023). "WDR5-0103 significantly blocked GAA-induced migration of pancreatic cancer cells." (PMID 37370109, 2023). "Therefore, we further inhibited WDR5 with WDR5-0103 to suppress H3K4me3 modification in pancreatic cancer cells." (PMID 37370109, 2023). "Interestingly, a study using patient-derived xenografts of pancreatic cancer demonstrated the WDR5:Myc interaction in vivo and showed this interaction prevented DNA damage accumulation." (PMID 29925347, 2018). "Importantly, WD Repeat Domain 5 (WDR5) is implicated in the dual regulation of tumour growth and immune evasion through its epigenetic control over MHC‐I expression and immunosuppressive pathways in pancreatic cancer." (PMID 40673641, 2025). "However, WDR5 expression is positively correlated with the HLA level in human cancer cells, and H3K4me3 enrichment is observed at the promoter region of the HLA-A, HLA-B, and HLA-C genes in pancreatic cancer cells." (PMID 39201460, 2024). "Our previous studies have shown that the expression of PD-L1 and OPN is regulated by the WDR5/MLL1-H3K4me3 pathway, and WDR5-47 effectively improved anti-PD-L1 efficacy in pancreatic tumor." (PMID 39201460, 2024). "Due to the unavailability of human pancreatic tumor scRNA-seq datasets, we then mined scRNA-seq datasets (GSE178341) and analyzed WDR5 expression profiles in human colon tumors." (PMID 39201460, 2024). "One prominent example is WDR5, which was one of the few tested MYC binding partners with an even greater dropout in pancreatic tumours than in cultured KPC cells." (PMID 38821858, 2024). "In this study, we report that WDR5 modulates the expression of MHC I and immune-suppressive cytokines in the pancreatic tumor microenvironment." (PMID 39201460, 2024). "On the other hand, WDR5 depletion leads to the effective downregulation of immune checkpoints and immunosuppressive cytokines, including TGFβ and IL6, in the pancreatic tumor microenvironments." (PMID 39201460, 2024). "In addition, WDR5 ablation effectively results in the downregulation of immune checkpoints (PD-1, PD-L1, and Spp1) and immunosuppressive cytokines (TGFβ and IL6) in pancreatic tumor microenvironments, leading to improved CD8+/CD4+ T-cell infiltration." (PMID 39201460, 2024). "To explain why Wdr5 depletion did not effectively promote tumor growth in the syngeneic pancreatic tumor model, we further analyzed immune cell profiles in the tumor microenvironment." (PMID 39201460, 2024). "For example, certain lncRNAs could interact with the WDR5/MLL complex to up‐regulate the expression of multiple 5’ HOXA genes, which played an regulatory role in the progression and chemoresistance of pancreatic cancer." (PMID 32239802, 2020). "Consistent with this proposed role by which WDR5 may support tumor growth and survival, depletion of KMT2D in multiple pancreatic cancer cell lines increased their responsiveness to 5-FU suggesting the possibility that KMT2/MLL inhibitors could be used for chemotherapy or radiation sensitization." (PMID 29925347, 2018).
neuroblastoma (11 papers, 2018 to 2024). Neuroblastoma (NB) is the most common solid, extracranial childhood tumor. "Beyond Burkitt lymphoma, WDR5 is thought to play a pro-tumorigenic role in various other cancers, including high-risk neuroblastoma, which is associated with amplification of the N-MYC gene, MYCN." (PMID 37336886, 2023). "In neuroblastoma, high levels of WDR5 expression are associated with poor survival in primary neuroblastoma cases." (PMID 31920530, 2019). "In both these cell lines, the interaction of WDR5 with PDPK1 is inhibited by the R3A mutation with a concomitant decrease in N-MYC binding, indicating that across multiple N-MYC amplified neuroblastoma cell lines N-MYC can associate with PDPK1 through their shared direct interactions with WDR5." (PMID 38605297, 2024). "Previously published WDR5 CUT&RUN data from HeLa S3 cells and WDR5 ChIP-seq data from human Be2C neuroblastoma cells were also obtained for comparison and analyzed using identical workflows." (PMID 39056772, 2024). "We first confirmed N-MYC can interact physically with WDR5 by performing immunoprecipitation (IP) for endogenous N-MYC in the N-MYC amplified neuroblastoma cell line, CHP-134." (PMID 37336886, 2023). "A previous study proved that Wdr5 regulated the transcription of Mdm2 in neuroblastoma via affecting the level of H3K4me3 at its promoter." (PMID 36358925, 2022). "Clinically, high expression of WDR5 in neuroblastoma were a valid indicator of unfavorable prognosis." (PMID 34658888, 2021). "In MYCN-amplified neuroblastomas, WDR5 functions as a core cofactor participating in transcriptional activation and tumorigenesis under the guidance of N-Myc." (PMID 34658888, 2021). "WDR5 expression is promoted by the N-MYC oncoprotein and is increased in neuroblastoma cells, which is associated with a poor prognosis of patients." (PMID 33302406, 2020). "Our previous study demonstrated that PHF20 interacts with WDR5 and plays an important role in cellular reprogramming and neuroblastoma aggressiveness." (PMID 33117706, 2020). "In this study, we focus on the intersection of N-MYC with two cellular regulators that have known ties to cell cycle processes—PDPK1 and WDR5—to understand how each contributes to mitotic gene regulation in neuroblastoma cells marked by overexpression of N-MYC." (PMID 38605297, 2024). "Unfortunately, it is currently unknown if WDR5 can recruit N-MYC to chromatin as has been shown for c-MYC, and unclear the extent of overlap between N-MYC and WDR5 in N-MYC amplified neuroblastoma specifically." (PMID 37336886, 2023). "Our data reveals that WDR5 acts as a universal MYC recruiter at a small cohort of previously identified genes and highlights novel biological functions that may be coregulated by N-MYC and WDR5 to sustain the neuroblastoma state." (PMID 37336886, 2023). "Therefore, knowing how much of this can be extended to N-MYC and N-MYC-amplified neuroblastoma is beneficial in determining the broad significance of WDR5 as a context-independent MYC cofactor." (PMID 37336886, 2023). "For example, WDR5 is a protein that exists as part of many chromatin regulatory complexes, and it is a histone H3K4 presenter that has been reported in association with neuroblastoma." (PMID 31920530, 2019). "Using RNA-seq analysis, we identify the genes regulated by N-MYC and PDPK1 in multiple engineered CHP-134 neuroblastoma cell lines and compare them to previously published gene expression data collected in CHP-134 cells following inhibition of WDR5." (PMID 38605297, 2024). "In N-MYC-amplified neuroblastoma cell lines, removal of WDR5 from cells also attenuates the ability of N-MYC to bind these same sites, indicating that WDR5 can recruit N-MYC to chromatin at specific regions of the genome as has been seen for c-MYC." (PMID 37336886, 2023).
neuroblastoma (continued). "Here, we focus on N-MYC amplified neuroblastoma to determine the extent of colocalization between N-MYC and WDR5 on chromatin while also demonstrating that like c-MYC, WDR5 can facilitate the recruitment of N-MYC to conserved WDR5-bound genes." (PMID 37336886, 2023). "The cooperation between WDR5 and MYC in neuroblastoma involves a direct interaction between them in the promoters of N-MYC target genes such as MDM2 and other protumorigenic genes, leading to H3K4 trimethylation and their activation." (PMID 33302406, 2020). "Using a variety of genetically engineered N-MYC amplified neuroblastoma cell lines, we identified a small group of genes highly enriched within functional gene categories related to mitotic processes that are commonly regulated by N-MYC, WDR5, and PDPK1." (PMID 38605297, 2024). "RNAi-mediated gene silencing of WDR5 or the inhibition of the N-MYC/WDR5 complex formation by a small molecule antagonist of WDR5 inhibits the expression of N-MYC target genes, which suppresses the growth of neuroblastoma cells." (PMID 33302406, 2020). "Therefore, to characterize the influence of WDR5 and PDPK1 on mitotic gene expression in cells with high MYC levels, we performed a comparative transcriptomic analysis in neuroblastoma cell lines defined by MYCN-amplification, which results in high cellular levels of the N-MYC protein." (PMID 38605297, 2024).
colon cancer (10 papers, 2018 to 2024). "Our data demonstrate that this is also likely the case in colon cancer cells, as WDR5 depletion caused global H3K4Me3 levels to decrease, which is believed to affect target gene transcription." (PMID 29925347, 2018). "To elucidate the functional link between WDR5 expression and response to chemotherapy, we next analyzed datasets of a recently published human colon cancer-patient clinical trial for combined PD-1, BRAF, and MEK inhibition." (PMID 39201460, 2024). "The effect of WDR5 on DDR and cancer sustaining was found in colon cancer studies, which showed that WDR5 depletion sensitized the colon cancer cells to radiation-induced DNA damage." (PMID 33302406, 2020). "This study demonstrated WDR5 is highly overexpressed in colon cancer cells and is essential for colon cancer cell viability." (PMID 29925347, 2018). "Further, we show that OICR-9429, an inhibitor of the interaction between KMT2/MLL and WDR5, is required for colon cancer growth." (PMID 29925347, 2018). "WDR5, RBBP5, and DPY30 are increased in tumors relative to normal tissue; however, WDR5 is expressed at the highest level and shows the most dramatic increase in expression between normal tissue and colon tumor tissue so it was selected for further study." (PMID 29925347, 2018). "WDR5 is over-expressed in gastric and colon cancer cell lines and human tumor tissues, and high levels of WDR5 expression in tumor tissues is associated with poor patient survival rate." (PMID 30488017, 2018). "Our data demonstrate that colon cancer cells rely on WDR5 for increased proliferation and cell survival as depletion of WDR5 reduced cell viability." (PMID 29925347, 2018). "Reassuringly, all four individual oligos and both pools reduced HCT116 viability as measured by alamarBlue® following WDR5 depletion by more than 30% in 72 h suggesting WDR5 itself is playing a role supporting colon cancer cells." (PMID 29925347, 2018). "In colon cancer cells, WDR5 decreases the phosphorylation of the histone protein H2AX and induces H3K4 trimethylation, leading to colon cancer cell proliferation and survival, and WDR5 depletion sensitizes colon cancer cells to radiation-induced DNA damage." (PMID 30488017, 2018). "Treatment with 10 μM OICR-9429 for 72 h also decreased cell viability (alamarBlue® Cell Viability Assay), but to a lesser extent than seen with WDR5 depletion in some colon cancer cell lines." (PMID 29925347, 2018). "Cell viability and colony forming assays were utilized to evaluate the effects of WDR5 depletion or inhibition in colon cancer cells." (PMID 29925347, 2018). "This may explain why, in general, the tumor size/weight did not change significantly after WDR5 deficiency, and non-responders to chemotherapy/immunotherapy exhibited an even-higher WDR5 level compared with responders in colon-cancer and melanoma patients." (PMID 39201460, 2024). "Moreover, WDR5 expression is negatively correlated with patients’ response to chemotherapy or immunotherapy in human colon cancer and melanoma." (PMID 39201460, 2024). "This positive feedback loop could be contributing to the consistent overexpression of WDR5 demonstrated here in both colon cancer cell lines as well as human colon tumors; however, this is difficult to definitively demonstrate experimentally." (PMID 29925347, 2018). "WDR5 is overexpressed in colon tumors and colon cancer cell lines at the mRNA and protein level." (PMID 29925347, 2018). "WDR5 depletion reduced cell ATP levels by 15–30% in six colon cancer cell lines." (PMID 29925347, 2018). "WDR5 depletion also sensitized colon cancer cells to radiation-induced DNA damage." (PMID 29925347, 2018). "OICR-9429 treatment was particularly toxic to SW620 and T84 colon cancer cells, two cell lines without mutations in WDR5 and KMT2/MLL proteins suggesting COMPASS complex inhibition may be particularly effective in tumors lacking KMT2 mutations." (PMID 29925347, 2018).
colon cancer (continued). "In this report, we show that WDR5, a common component of the SET/MLL COMPASS complex, is overexpressed in human colon cancer tumors and cell lines and is required for colon tumor cell proliferation." (PMID 29925347, 2018). "For example, WDR5 has been shown to promote EMT by promoting mesenchymal gene activation and binding to ZNF407 to promote colon cancer metastasis." (PMID 29925347, 2018). "WDR5 depletion reduces cell viability in HCT116, LoVo, RKO, HCT15, SW480, SW620, and T84 colon cancer cells." (PMID 29925347, 2018). "Treatment with OICR-9429 was particularly efficacious in SW620 and T84 cells; however, in other colon cancer cell lines, OICR-9429 was less effective than direct RNAi-mediated depletion of WDR5." (PMID 29925347, 2018). "Additionally, disrupting the scaffolding capabilities of other histone methyltransferase complexes, through the use of WD repeat-containing protein 5 (WDR5) inhibitors, demonstrated antitumor efficacy in preclinical models of colon cancer." (PMID 38915093, 2024). "WDR5 has been implicated in cancer for its role in the COMPASS complex and its interaction with Myc; however, the role of WDR5 in colon cancer has not yet been elucidated." (PMID 29925347, 2018). "WDR5 is also overexpressed at the mRNA and protein level in a panel of colon cancer cells as compared to immortalized, yet non-transformed human colon epithelial cells (HCECs) suggesting WDR5 may play a pro-tumorigenic role in colon cancer." (PMID 29925347, 2018). "The contribution of WDR5 to DNA fidelity may or may not be independent of its role in the WRAD subcomplex as RBBP5 did not affect viability in a panel of colon cancer cells." (PMID 29925347, 2018). "WDR5 depletion reduced H3K4Me3 and increased phosphorylation of H2AX in HCT116, SW620, and RKO colon cancer cells; however, OICR-9429 treatment did not recapitulate these effects in all cell lines potentially explaining the reduced toxicity of OICR-9429 treatment as compared to WDR5 depletion." (PMID 29925347, 2018).
acute myeloid leukemia (8 papers, 2018 to 2026). Acute myeloid leukemia (AML) is a group of neoplasms arising from precursor cells committed to the myeloid cell-line differentiation. "Applying CycloSEL to the acute myeloid leukemia target WD repeat-containing protein 5 (WDR5) yields a macrocycle with subnamolar affinity, and potent inhibition of the WDR5-Mixed-Lineage Leukemia 1 (MLL1) interaction." (PMID 41963347, 2026). "Interestingly, the WDR5 degrader inhibits the proliferation of acute myeloid leukemia and reduces the level of chromatin-bound c-myc, which is critical in T-ALL pathogenesis." (PMID 36483601, 2022). "Several WDR5 inhibitors are in clinical trial for the treatment of acute myeloid leukemia." (PMID 36249032, 2022). "Similarly, high expression of WDR5, particularly when combined with high expression of MLL1, is correlated with high-risk acute lymphoblastic leukemia (ALL) and acute myeloid leukemia (AML)." (PMID 29498679, 2018). "The C/EBPα p30 mutant protein drives acute myeloid leukemia by forming a protein complex with WDR5." (PMID 30488017, 2018). "In acute myeloid leukemia (AML) harboring MLL rearrangement (MLL-r AML), the complex assembled by WDR5 and wild-type (WT) MLL cooperates with the MLL-r chimeric oncoproteins to sustain an oncogenic gene expression program, and depletion of the WDR5-MLL1 complex suppresses the growth of MLL-r AMLs." (PMID 34586829, 2021).
hepatocellular carcinoma (7 papers, 2016 to 2024). A malignant tumor that arises from hepatocytes. "In hepatocellular carcinoma (HCC), the expression of HOXA locus gene was co-regulated by HOTTIP and WDR5/ mixed lineage leukemia 1 (MLL1) complex." (PMID 27429196, 2016). "Furthermore, we observed HBV up-regulates ALKBH5 via the HBx-WDR5-H3K4me3 axis, and ALKBH5 forms a positive feedback loop with HBx to lead to hepatocellular carcinoma progression." (PMID 34112124, 2021).
liver cancer (6 papers, 2015 to 2026). An epithelial or non-epithelial malignant neoplasm that arises from the liver. "For instance, overexpression of WDR5 is not only associated with the development and progression of various cancers, such as prostate cancer, breast cancer, leukemia, and liver cancer, but also linked to unfavorable clinical outcomes." (PMID 38744853, 2024). "Through the adsorption of miR-940 via sponging, CCDC144NL-AS1 stimulates the production of WDR5, and since CDK1, CKD2, and CDK4 are all downstream targets of WDR5, this promotes the development of liver cancer." (PMID 37240281, 2023). "Besides being present in the extracellular space, PTENα and PTENβ are also prominently localized in the nucleus and promote liver cancer cell growth by interacting with WDR5 protein through their NTEs." (PMID 38744853, 2024). "The previous study has shown that PTENα/β promotes tumor progression in liver cancer cells by interacting with WDR5 to recruit the SET1/MLL complexes to the promoters of the PTENα/β-target genes, such as NOTCH3, SLC12A5 and TCF19, the broadly studied oncogenes." (PMID 38744853, 2024). "Therefore, a potential therapeutic strategy for liver cancer could involve combining a PTENα/β-WDR5 protein-protein interface inhibitor with an activator of Furin." (PMID 38744853, 2024). "Inhibiting WDR5 with small‐molecule inhibitor WDR5‐0103 significantly suppresses HBV and HBx‐driven tumor growth, suggesting that WDR5 plays a critical role in HBV‐induced liver cancer." (PMID 40060195, 2025). "However, because another MYC family member, N-MYC, also reportedly binds to the CACGCG motif in the WDR5 gene promoter, we cannot rule out the involvement of N-MYC, which plays a critical role in liver cancer stem cells." (PMID 31739577, 2019).
cholangiocarcinoma (5 papers, 2021 to 2025). A carcinoma that arises from the intrahepatic biliary tree (intrahepatic cholangiocarcinoma) or from the junction, or adjacent to the junction, of the right and left hepatic ducts (hilar cholangiocarcinoma). "Recent research has identified that WDR5 promotes epithelial–mesenchymal transition (EMT) and metastasis in cholangiocarcinoma by enhancing HIF-1α accumulation through MYC-dependent pathways." (PMID 39757165, 2025). "In several studies, WDR5 promoted HIF-1α activity and HIF-1α was reported to be an important effector in WDR5-induced cholangiocarcinoma metastasis under 95% air and 5% CO2 instead of hypoxia treatment." (PMID 39757165, 2025). "WDR5 could interact with the MBIIIb motif of c-Myc and facilitate Myc-induced HIF1-α transcription, therefore promoting the EMT, invasion and metastasis of cholangiocarcinoma (CCA)." (PMID 34658888, 2021).